IL10 (interleukin 10)
Diseases named in the same sentence as IL10 in open-access papers (continued):
Sharing a sentence is not in itself a finding about the gene and the disease.
lupus (continued). "Although these peptide autoantigens can drive pathological processes in lupus, interestingly they can also induce tolerance by influencing increased regulatory T-cell (Treg) activity, or by stimulating production of anti-inflammatory cytokines such as IL-10." (PMID 27487771, 2016). "In addition, we also investigated IL-10, an immunomodulatory cytokine that is highly upregulated in human and murine lupus." (PMID 27070142, 2016). "Given the recent interest in regulatory B cells, we hypothesized that IL-10 production by CD5+ B cells was critical to suppression in our lupus-prone mice." (PMID 26964093, 2016). "However, MZ B cells can secret IL6 upon the treatment of LPS in combination with CD40L, indicating the different underlying mechanisms for IL10 and IL6 production by MZ B cells in lupus-prone mice." (PMID 26068236, 2015). "Moreover, miR-21 has been observed to suppress PDCD4 expression, thus enhancing cell proliferation and increasing CD40L and IL-10 expression in lupus T cells." (PMID 25988383, 2015). "Evidence suggesting that B cell-derived IL10 may play an insignificant role during lupus progression in lupus-prone MRL-Faslpr/lpr mice." (PMID 26068236, 2015). "IL-10 is a key cytokine produced by Breg cells, and diminished disease severity was observed following administration of IL-10 in the NZM2410 mouse model of lupus, whereas more severe disease occurred in both MRL/lpr mice on a IL-10 KO background and in Breg cell-deficient NZB/W mice." (PMID 24551101, 2014). "In addition, CD24hiCD38hi B cells isolated from theperipheral blood of systemic lupus erythematosus patients were refractory to CD40 ligation andproduced less IL-10 compared with their healthy counterparts." (PMID 23566714, 2013). "Recently identified IL-10 producing regulatory B cells (Bregs) may exert immunosuppressive effects to modulate murine lupus." (PMID 24130510, 2013). "Together, these data indicate that Tfh cell-derived IL-21 may be one of promoting factors for IL-10 production in lupus, which is consistent with the recently Nature published results that IL-21 is important for B10 cell development and expansion." (PMID 23638156, 2013). "In addition, it has been reported that over-expression of IL-10 in lupus-prone NZM2410 mice can ameliorate lupus diseases." (PMID 24319531, 2013). "Our finding that IL-21-induced IL-10 production provided, at least in part, an explanation for the elevated IL-10 in lupus suggested that micro-environmental cytokines or factors may be involved in the development of B10 cells and autoimmune regulation." (PMID 23638156, 2013). "Consistent with above results in vitro, MBL treatment could suppress the pro-inflammatory cytokine TNF-α, MCP-1 and IL-6 while increase the expression of IL-10 in the renal macrophages and in serum of lupus mice." (PMID 23626823, 2013). "Moreover, continuous administration of anti-IL-10 antibodies in a murine lupus model delayed the onset of autoimmunity and improved the survival rate from 10 to 80%." (PMID 24319531, 2013). "Disease severity in human and murine lupus is also tightly correlated to IL-10." (PMID 22389703, 2012). "It was reported that patients with lupus produced large amount of IL-10." (PMID 22389703, 2012). "Further, Avemar decreased inflammation through other immunomodulatory mechanisms, such as decreased production of pro-inflammatory cytokines IL-6 and IL-10 in mice with systemic lupus erythematosus and decreased macrophage infiltration in animal models of rheumatoid arthritis." (PMID 19622599, 2011). "Longitudinal studies on lupus nephritis patients have shown a significant decrease in IL-10 levels from the time of inclusion to remission; at remission, IL-10 concentrations became comparable to those observed in SLE patients with inactive disease." (PMID 40244128, 2025). "Studies have reported that the number and function of IL‐10 producing Bregs are impaired in murine lupus and human SLE." (PMID 39737854, 2025).
lupus (continued). "Conversely, studies have also found that in systemic lupus erythematosus (SLE), loss of PGRN reduces Th1, Th17, IFN-γ, and IL-17A levels, whereas it increases Th2, Treg, Breg, IL-4, and IL-10 levels." (PMID 40290306, 2025). "While UVB radiation can up-regulate Th2 cells and down-regulate Th1 cells, induce IL-10 production, increase type I IFN expression, and prolong T cell activation to increase SLE risk, another subset of UV radiation, UVA, is used as a phototherapy modality to treat cutaneous forms of lupus." (PMID 39318630, 2024). "In another study, the oral intake of RJ reduced the number of splenic autoreactive B cells, serum IL-10 levels, and anti ssDNA, dsDNA, and erythrocyte autoantibodies in systemic lupus erythematosus (SLE)-prone New Zealand Black × New Zealand White F1 mice." (PMID 38892209, 2024). "Co-vaccination with IL-10 reduced tubular damage in mouse models with induced systemic lupus erythematosus (SLE) nephropathy." (PMID 37762322, 2023). "Interestingly, we found similar populations of IL-10 producing cells from scRNA-seq of lupus-prone mice as these markers were expressed by the Phagocytic PB-PC and TIM-1 B Cell populations from pre-disease mice and the TACI/TNF B Cell and TIM-1 B Cell populations from active-disease mice." (PMID 38155972, 2023). "Since IL-10 signaling pathway was up-regulated in overall monocytes at MC, we next analyzed the expressions of ribonuclease A family member 2 (RNASE2) which can induce IL-10 secretion from monocytes and thus augment the age-associated B cells expansion in systemic lupus erythematosus." (PMID 37620910, 2023). "However, studies in murine models indicate that IL-10 can also play a protective role in lupus." (PMID 35979356, 2022). "Elevated levels of IL-10 have been reported in chronic inflammatory diseases such as systemic lupus erythematosus (SLE), rheumatoid arthritis (RA), systemic sclerosis (SSc), and adult-onset Still’s a disease (AOSD)." (PMID 35455984, 2022). "And then there are the potent TPH cells with TFH like phenotype but are CXCR5-; they help lupus B cells also by producing IL-21; and IL-10–producing CCR6+T cells populate lymph nodes of SLE patients." (PMID 33936042, 2021). "In our study, the reductions of IL-10+ Breg cells and serum IL-10 were accompanied by reduced serum IL-35, suggesting that IL-35 may be responsible for the regulatory function of Breg cells on lupus in MRL/lpr mice." (PMID 33240280, 2020). "Additionally, miR-199a was shown to target PARP-1 and activate the ERK1/2 pathway to promote IL-10 production, suggesting that miR-199a may be a potential therapeutic target of systemic lupus erythematosus." (PMID 33276722, 2020). "IL-10 is known to be elevated in the serum and tissues of patients with systemic lupus erythematosus (SLE) and the expression of IL-10 is activated by Stat3 (signal transducer and activator of transcription 3) in peripheral CD4+ T cells." (PMID 30816218, 2019). "In MRL.Faslpr mice, a complete deficiency in IL-10 was accompanied by an enhanced IFNγ production in both CD4+ and CD8+ T cells, and an elevated anti-dsDNA antibody production with more severe clinical diseases, suggesting a protective role of IL-10 in lupus development." (PMID 31546763, 2019). "Recent research has further revealed that lupus B cells with enhanced PD-1 expression exhibit functionally reduced proliferation along with reduced PD-L1 up-regulation capacity upon stimulation by interleukin-2(IL-2)/IL-10, anti-B cell receptor (anti-BCR), CpG, and CD40L." (PMID 31597242, 2019). "It warrants a further study whether the IL-10 also plays a role in B7-H4 signal in lupus." (PMID 29321778, 2017). "In contrast, sCTLA-4 blockade in resting PBMC from SLE patients raised both cell proliferation and IL-10 levels, suggesting that PBMC in lupus patients seem primed to secrete higher levels of IL-10." (PMID 27487771, 2016).
lupus (continued). "Decreased frequency and dysfunction of IL-10+ Bregs have been described in humans with various autoimmune disorders such as rheumatoid arthritis, systemic lupus erythematosus (SLE), inflammatory bowel disease, graft-versus-host disease, and vasculitides." (PMID 27437104, 2016). "For example in systemic lupus erythematosus (SLE), IL-10 is directly able to induce the expression of Fas on the surface of T cells resulting in increased levels of apoptosis." (PMID 27505056, 2016). "Our previous work has shown that the expansion of IL-10-producing B cells correlates with disease suppression in bicongenic B6.NZBc1c4 mice and that transfer of B6.NZBc4 splenic B cells reduces the frequency of pro-inflammatory T cells in B6.NZBc1 lupus-prone recipient mice." (PMID 26964093, 2016). "In particular, the expressions of TNF-α, IL-6 and IL-10 are markedly elevated in SLE patients with lupus nephritis." (PMID 24629023, 2014). "By using IL-10 gene-knockout (IL-10−/−) mice, we demonstrated recently that, in the absence of IL-10 even the resistant strain could be rendered susceptible to the induction of a typical lupus-like renal disease." (PMID 24491821, 2014). "Rosado and coauthors and Chen and coauthors have shown higher sHLA-G and IL-10 levels in systemic lupus erythematosus (SLE) patients in comparison with healthy controls, while Rizzo and coauthors have observed lower sHLA-G concentrations in SLE patients." (PMID 25477881, 2014). "Therefore, the exact role of IL-10 in lupus remains to be established." (PMID 22321827, 2012). "Inhibition of IL-10 activity by neutralizing antibodies results in decreased expression of disease markers in both SLE patients and murine models of lupus." (PMID 23554785, 2012). "However, inhibitory cytokine IL-10 was notably increased in pSAP-treated lupus mice, which might also partly contribute to the alleviation of lupus nephritis." (PMID 21799927, 2011). "However, levels of IL-10 were notably increased in the pSAP-treated lupus mice." (PMID 21799927, 2011). "Increased levels of IL-10 have been found in the sera of lupus patients and genetic variations of IL-10 gene promoter have been found in SLE patients in different ethnic populations." (PMID 27713252, 2010). "As for IL-10, elevated in both SLE and severe COVID-19, promotes B-cell activation in lupus but also reflects immune regulation." (PMID 40643149, 2025). "In line with our findings, it has been described that in lupus patients, CD19+CD24hiCD38hi B cells exhibited reduced regulatory capacity and reduced IL-10 secretion." (PMID 40761803, 2025). "After 24 h of DW treatment, there was a noticeably decrease in frequency of CD19+ cells and increase in frequency CD19+ CD24+ CD27+, CD19+ CD24+ CD27+ IL-10+ Breg memory cells and CD19+ IL-10+ Bregs compared with untreated cells (lupus)." (PMID 40158179, 2025). "NK-cells play diverse functions in murine lupus producing cytokines such as IFN-γ, TNF-α, GM-CSF, interleukin (IL)-10, and IL-13 upon stimulation." (PMID 40806179, 2025). "Disease activity, measured by Systemic Lupus Erythematosus Disease Activity Index (SLEDAI) score, correlated positively with Th10 cells and IL-10 levels." (PMID 39099913, 2024). "Furthermore, the authors indicated that the high IL-10 levels may be attributed not only to Tregs and Tr1 cells but also to IL-10-producing B cells, which have been documented in multiple sclerosis and systemic lupus erythematosus and in the natural tolerance of renal transplant recipients." (PMID 39340024, 2024). "In a study on pristane-induced lupus in BALB/c mice, baicalin reduced the production of proinflammatory cytokines such as TNF-α, IL-6, IL-10, and IFN-γ." (PMID 37511964, 2023). "An in vitro study on pristane-induced lupus BALB/c mice found that the use of S. baicalensis downregulated the production of proinflammatory cytokines such as TNF-α, IL-6, IL-10, and IFN-γ." (PMID 37511964, 2023).
lupus (continued). "For example, the neutralizing humanized anti-IL-10 mAb, BT063, is being investigated in a phase 2 trial (NCT02554019) for the treatment of systemic lupus erythematosus (SLE)." (PMID 37513979, 2023). "In the LFRR cohort, IL-10 was highest in lupus relatives who were clinically unaffected, while active TGF-β, as well as IFN-γ and TNF-α, were elevated in lupus relatives with ILE." (PMID 35720322, 2022). "A study found that in Murphy Roths Large (MRL)/lpr mice, a spontaneous lupus-like disease model, the reduction of IL-10+ Breg cells and serum IL-10 were accompanied by reduced serum IL-35, prompting that IL-35 may be involved in the regulatory function of Breg cells from lupus." (PMID 35434379, 2022). "To verify the effect of RNASE2 on IL-10 secretion, we isolated CD14+ monocytes from lupus PBMCs by magnetic beads and cultured with RNASE2 siRNA." (PMID 35265065, 2022). "In addition to PMN, Treg and IL-10 also serve as critical therapeutic factors in systemic lupus erythematosus (SLE)." (PMID 36210816, 2022). "Studies have indicated high levels of IL-10 in SLE patients and mouse models of lupus." (PMID 35359961, 2022). "Conversely, the regulatory mediators IL-10 and active TGF-β, as well as IFN-γ, were lowest in HC and lupus relatives in the LAUREL cohort who met clinical ACR criteria at baseline." (PMID 35720322, 2022). "It has been shown that Tfh cells could secrete IL-21 and thus facilitate Breg cell differentiation and production of IL-10 in systemic lupus erythematosus (SLE)." (PMID 36339942, 2022). "This study found a correlation between CD38 with FoxP3 expression and immunosuppressive molecules (CD69, IL-10, CTLA-4, and PD-1) in T-cells from lupus-prone mice (B6.MRL-Faslpr/J)." (PMID 34769406, 2021). "This was explored in lupus-prone NZB/W F1 mice in vitro and vivo to understand IL-10 effects on individual immune cells as well as in the complex in vivo setting." (PMID 33572870, 2021). "Of note, recent drug trials in lupus included testing of compound BT063, a monoclonal humanized anti-IL-10 antibody; tested for safety and tolerability." (PMID 32655565, 2020). "It is interesting to note that monocytes from systemic lupus erythematosus have defects in adhesion and produce elevated levels of IL-6, TNF-a, and IL-10 than healthy monocytes." (PMID 32645059, 2020). "A study on systemic lupus erythematosus showed that miR-410 downregulates IL6 and IL10 expression, and its overexpression significantly reduced the expression levels of TGF-b1 in SV40MES13 cells." (PMID 33005638, 2020). "SLE patients also showed the similar tendency with MRL mice; the expression level of Ctse and IL10 mRNAs in CD4+ T cells is upregulated in lupus patients than healthy control, while PDCD4 mRNA lower tendency in lupus patients than healthy control." (PMID 30816218, 2019). "In lupus-prone MRL/Lpr mice, successive administration of anti-CD40 antibodies remarkably induced the expansion of IL-10-secreting transitional B cells, along with ameliorated lupus nephritis development." (PMID 31795353, 2019). "Furthermore, as a key regulatory factor in the pathogenesis of systemic lupus erythematosus (SLE), miR-410-3p was found to be decreased in T cells of SLE patients and regulated the expression of IL-10." (PMID 30242542, 2019). "Treatment with IL-35 significantly increased the numbers of IL-10-secreting CD1d+CD5+ Bregs and ameliorated renal damages in lupus-prone MRL/Lpr mice." (PMID 31795353, 2019). "Further, we showed that TGF-β3 ameliorated lupus pathologies with suppressing TFH cells and antibody-producing cells while maintaining total CD4+ T cells and B220+ B cell count in IL-10-sufficient MRL/lpr mice." (PMID 29963056, 2018). "New evidence provided from current study demonstrates that CD8+CD103+iTreg suppress lupus B cells also via TGF-β and IL-10 signals since these lupus B cells indeed maintain the expression of TGF-β and IL-10 receptors." (PMID 29441062, 2018).
lupus (continued). "Among those genes, IL10 and IL1R2 genes present a range of methylation-regulated domain variance in lupus." (PMID 28785369, 2017). "PBMC from healthy donors responded to each of the lupus peptides by secreting IFN-γ and IL-17, but PBMC from SLE patients produced IL-10." (PMID 27487771, 2016). "The employment of a dual reporter mouse where Blimp1 and IL-10 competency could be simultaneously evaluated allowed us to obtain unique insights into the differential ability of distinct DC subsets to express these crucial molecules in the context of a lupus model." (PMID 26544714, 2015). "Our study also confirms and strengthens previous reports on increased levels of IL-6, IL-10, TNF-α, IFN-γ, IL-17 and IL-23 as well as low TGF-β in lupus patients." (PMID 25887118, 2015). "Here, we investigated the percentages of Tfh cells and B10 cells in lupus-prone MRL/Mp-lpr/lpr (MRL/lpr) mice and examined the effects and mechanism of Tfh cell-derived interleukin-21 (IL-21) on IL-10 production during the differentiation of B10 cells." (PMID 23638156, 2013). "Our previous reports have demonstrated that SM934 could modulate autoimmune responses in systemic lupus erythematosus (SLE) via enhancing the secretion of IL-10 by macrophages to repress both Th1 and Th17 responses." (PMID 24009768, 2013). "Although early reports demonstrated defective Th1 and excessive Th2 responses in lupus, recent data suggest that the levels of both Th1 (IFN-γ, IL-12, and IL-18) and Th2 (IL-4, and IL-10) cytokines are increased in the sera of lupus patients." (PMID 22761630, 2012). "Also, in a mouse model of systemic lupus erythematosus (SLE), MZ B cells have been shown to respond to CpG by secretion of IL-10." (PMID 17918201, 2007). "IL-10–producing FOXP3– (non-Treg) CD4+ T cells are expanded in lupus, including in W.Yaa mice, and the frequency of these cells was not affected by DON." (PMID 40956613, 2025). "The study further revealed that CD19-/- lupus-prone mice failed to produce a subset of interleukin-10 (IL-10)–producing regulatory B cells (Bregs), which are known to play a critical role in immune regulation." (PMID 40977680, 2025). "The correlation between gut mycobiota and lupus characteristics, including anti-dsDNA, urine protein creatinine index (UPCI), and serum cytokines (IL-6, TNF-α, and IL-10) were examined using the NMDS with length and direction of vectors to represent strength and direction of the association." (PMID 39637140, 2024). "In addition to type I IFN signature genes, many other hypomethylated genes (such as CD70, ITGAL, IL10, and IL17) have been identified in lupus cells, which contributed to abnormal immune cell activation and inflammation in lupus." (PMID 38153351, 2023). "Moreover, studies with azithromycin and monocytes from systemic lupus erythematosus patients revealed that the PI3K signalling pathway is involved in the regulation of cytokine secretion (IL-6, IL-1β, IL-10)." (PMID 35742807, 2022). "Recent studies now imply that IL-10 could be of crucial relevance for B cell differentiation in SLE and murine lupus, particularly for the extrafollicular response." (PMID 35979356, 2022). "However, genetic defects in IL-10 lead to more severe glomerulonephritis in mice with lupus in the MRL background, and IL-10 downregulates IFN-γ in the early stages of lupus to inhibit the pathogenicity of Th1 cells and delay the progression of lupus." (PMID 35359961, 2022). "In fact, our group identified macrophages and T cells, but not B cells, as major producers of IL-10 in murine lupus." (PMID 35192551, 2022). "Conversely, increased plasma levels of IL-10 were found in lupus relatives who did not report type 2 symptoms, particularly for fatigue." (PMID 35720322, 2022). "Although not necessarily significant, IL-10 levels trended higher in lupus relatives who did not report type 2 symptoms." (PMID 35720322, 2022).